MCM10 (minichromosome maintenance 10 replication initiation factor)
Diseases named in the same sentence as MCM10 in open-access papers (continued):
Sharing a sentence is not in itself a finding about the gene and the disease.
lung cancer (6 papers, 2021 to 2023). A malignant neoplasm involving the lung. "Ki67 is a well-established proliferation marker and MCM10 (minichromosome maintenance complex component 10) increased levels in lung cancer cells have been shown to correlate with recurrence and poor prognosis." (PMID 37880798, 2023). "MCM2-8 and MCM10 were highly expressed in paired lung cancer samples and may be involved in the development of lung cancer through the cell cycle and DNA replication." (PMID 35360518, 2022).
glioma (5 papers, 2021 to 2023). A benign or malignant brain and spinal cord tumor that arises from glial cells (astrocytes, oligodendrocytes, ependymal cells). "On the other hand, up-regulated MCM3-MCM8 and MCM10 were significantly associated with shorter disease-specific survival (DSS) in glioma patients." (PMID 36465369, 2022). "On the other hand, up-regulated MCM2-MCM8 and MCM10 were significantly associated with shorter disease-specific survival (DSS) in glioma patients." (PMID 36465369, 2022). "We found that higher expressions of MCM2-MCM8 and MCM10 were linked with poor overall survival (OS) and progression-free survival (PFS) in glioma patients." (PMID 36465369, 2022). "In glioma, the knockdown of MCM10 in glioma cells resulted in decreased cell proliferation, migration and invasion." (PMID 35664337, 2022). "More importantly, we uncover that higher expression of MCM2-MCM8 and MCM10 were linked with poor OS and PFS in glioma patients." (PMID 36465369, 2022). "Receiver operator characteristic (ROC) curve analysis results confirmed that MCM2-MCM7, MCM9, and MCM10 had high accuracy (AUC > 0.80) in predicting glioma." (PMID 36465369, 2022). "Furthermore, MCM5, MCM8, and MCM10 CNV affect the prognosis of glioma patients." (PMID 36465369, 2022). "Furthermore, MCM5, MCM8, and MCM10 CNV affected the prognosis of glioma patients." (PMID 36465369, 2022).
ovarian carcinoma (5 papers, 2022 to 2024). A malignant neoplasm originating from the surface ovarian epithelium. "The overabundance of MCM10 was linked to unfavorable outcomes in cases of ovarian cancer and prostate cancer." (PMID 38870259, 2024). "Since MCM10 expression in ovarian cancer seems to show opposite effects related to patient survival, we analyzed and enriched genes with differential MCM10 expression in ovarian cancer." (PMID 37848534, 2023). "In ovarian cancer, MCM10 expression, on the other hand, showed a weak correlation with immune cell infiltration, which may be one of the reasons why MCM10 expression in ovarian cancer seems to show opposite effects related to patient survival." (PMID 37848534, 2023). "This aroused great interest in us, and thus we are also conducting related experiments to deeply explore the potential role of MCM10 in ovarian cancer and whether it may serve as a potential therapeutic target." (PMID 37848534, 2023). "Mutual-exclusivity analysis between MCM10 and multiple-immune checkpoints in ovarian cancer." (PMID 35664337, 2022). "Moreover, in ovarian cancer, MCM10 expression was also weakly correlated with immune cell infiltration, which may be related to immune escape from the tumor." (PMID 37848534, 2023). "Unlike in ovarian cancer where MCM10 gene variation is mainly concentrated on amplification, the variation of MCM10 is mainly concentrated on mutations in UCEC, which might be a potential mechanism of our finding that both of MCM10 mRNA and protein were overexpressed in UCEC tissue." (PMID 37246638, 2023). "However, we currently still do not know the relationship between MCM10 and ovarian cancer (OV) prognosis and immune checkpoints." (PMID 35664337, 2022).
urothelial carcinoma (5 papers, 2016 to 2022). A malignant neoplasm derived from the transitional epithelium of the urinary tract (urinary bladder, ureter, urethra, or renal pelvis). "For urothelial carcinoma, high MCM10 levels were significantly correlated with advanced tumors stages, vascular invasion, and nodal status." (PMID 30254986, 2018). "We have identified MCM10 as a marker of urothelial carcinoma progression with prognostic value for both upper and lower urinary tract cancers." (PMID 27780919, 2016). "Since high gene expression and protein production strongly correlates with negative outcomes, the detection of Mcm10 protein levels could be a valuable early indicator of progression in urothelial carcinomas." (PMID 28218679, 2017). "Moreover, a recent analysis of urothelial carcinomas found that the level of MCM10 expression, but not of other MCM genes, was a highly significant predictor of both disease-free and metastasis-free survival." (PMID 28218679, 2017).
hepatocellular carcinoma (4 papers, 2020 to 2025). A malignant tumor that arises from hepatocytes. "RIP-qPCR analysis confirmed a direct interaction between IGF2BP3 and MCM10 mRNA in hepatoma cells, with METTL3-WT interacting stronger than METTL3-3A." (PMID 40651967, 2025). "Although O-GlcNAcylation of METTL3 had minimal effect on its subcellular localization and methyltransferase activity, it enhanced its interaction with WTAP, thereby sustaining m6A levels in hepatoma cells and stabilizing MCM10 mRNA via IGF2BP3." (PMID 40651967, 2025). "To assess the role of MCM10 and its correlation with METTL3 in HCC progression, we found that knockdown of MCM10 inhibited the proliferation, invasion, and migration of hepatoma cells, while overexpression of MCM10 rescued the malignant phenotypes in METTL3-deficient cells." (PMID 40651967, 2025). "For hepatocellular carcinoma (HCC), we performed a tumor classification using a 4-gene signature (CYP26B1, MCM10, SPINK4, and TRIM54) derived from differentially expressed genes (DEGs) associated with ubiquitination." (PMID 38870259, 2024).
neuroblastoma (4 papers, 2021 to 2025). Neuroblastoma (NB) is the most common solid, extracranial childhood tumor. "We analyzed samples obtained from patients with neuroblastoma, revealing that higher levels of MCM2 and MCM10 mRNA were associated with poor survival rate." (PMID 35056094, 2021). "Therefore, these experiments confirm the dependence of MCM2 and MCM10 in neuroblastoma cells, and can be cellular targets for the development of drug therapy." (PMID 35056094, 2021). "The survival rates were not significantly changed in patients with high or low expression of MCM2 or MCM10 with MYCN-amplified neuroblastoma, suggesting that MYCN amplification is more dominant than MCM expression in determining poor prognosis in this patient subgroup." (PMID 35056094, 2021). "Moreover, the MCM10 expression is activated by some oncogenes, such as N‐MYC and Ewing's sarcoma‐derived oncogenes in neuroblastoma and Ewing's tumors." (PMID 34185429, 2021). "MCM10, MCM2, MCM3, and MCM6 are among the high-risk signature correlating with poor prognosis in both MYCN-amplified and MYCN-non-amplified neuroblastoma." (PMID 35056094, 2021). "BI-2536 may exert multiple effects on neuroblastoma cell death through inhibition of MCM2 and MCM10." (PMID 35056094, 2021).
prostate carcinoma (4 papers, 2021 to 2024). A carcinoma that arises from epithelial cells of the prostate gland. "Cui et al9 presented that knockdown of MCM10 suppresses prostate cancer cell malignant phenotype." (PMID 37860833, 2023). "Moreover, Cui and colleagues revealed that MCM10 was significantly upregulated in prostate cancer." (PMID 37746664, 2023).
restrictive cardiomyopathy (4 papers, 2021 to 2024). A type of heart disorder referring to the inability of the ventricles to fill with blood because the myocardium (heart muscle) stiffens and looses its flexibility. "A c.764 + 5G > A variant was identified in MCM10, in trans with a c.236del p.(Gly79fs) in a patient with restrictive cardiomyopathy." (PMID 37946251, 2023). "Recent in vitro studies using human cell lines showed that MCM10 is critical for human telomere replication and suggest that defective telomere maintenance caused both MCM10-associated natural killer (NK) cell deficiency and restrictive cardiomyopathy with hypoplasia of the spleen and thymus." (PMID 37437546, 2023). "We previously reported compound heterozygous variants of MCM10 that caused NKD and restrictive cardiomyopathy, respectively." (PMID 38262603, 2024). "Here, we describe compound heterozygous MCM10 variants in patients with distinctive, but overlapping, clinical phenotypes: natural killer (NK) cell deficiency (NKD) and restrictive cardiomyopathy (RCM) with hypoplasia of the spleen and thymus." (PMID 33712616, 2021).
cardiomyopathy (3 papers, 2021 to 2024). A disease of the heart muscle or myocardium proper. "We propose that this is also the case for MCM10 and that telomere erosion due to MCM10 deficiency was the cause of cardiomyopathy in these patients." (PMID 33712616, 2021). "We also reported a second more severe combination of human variants in MCM10 that caused fetal demise due to cardiomyopathy and underdeveloped thymus and spleen, consistent with the idea that cell type specific requirements for the level of MCM10 expression exist." (PMID 38262603, 2024).
colorectal cancer (3 papers, 2013 to 2023). A primary or metastatic malignant neoplasm that affects the colon or rectum. "Therefore, we hypothesized that NOLC1 plays an indispensable role in the regulation of the occurrence and development of colorectal cancer, and it may promote the invasion and metastasis of colorectal cancer together with MCM10, HELLS, and Noc3L-related genes." (PMID 37670166, 2023). "In addition, NOLC1 may be associated with MCM10, HELLS, NOC3L, and other genes through participating in Wnt signaling pathways and jointly regulate the occurrence and development of colorectal cancer under the influence of the tumor microenvironment and many other influencing factors." (PMID 37670166, 2023).
melanoma (3 papers, 2021 to 2024). A malignant, usually aggressive tumor composed of atypical, neoplastic melanocytes. "In the present study, we found that MCM10 was overexpressed in melanoma compared with its expression in normal skin, and showed significant differences in expression at the T and pathological stages." (PMID 34490114, 2021). "High mRNA levels of MCM4, MCM5, and MCM10 were closely related to worse prognosis in patients with melanoma." (PMID 34490114, 2021). "We found that the elevated expressions of MCM2–6 and MCM10 were significantly expressed in melanoma compared to normal skin." (PMID 34490114, 2021). "In summary, we detected elevated expression levels of MCM2–6 and MCM10 in melanoma and found that increased MCM4/5/10 mRNA levels were associated with a worse prognosis for patients with melanoma." (PMID 34490114, 2021). "Very recently, it was found that melanoma is characterized by elevated expressions of MCM-2–6 and MCM-10 proteins." (PMID 34959411, 2021). "The results revealed MCM1–7 protein levels were higher in melanoma tissues than in normal skin tissues, consistent with the results of MCM mRNA expression, whereas MCM9 and MCM10 proteins showed no great difference between melanoma and normal skin." (PMID 34490114, 2021).
breast tumor (2 papers, 2018). "The inhibitory effect of MCM10 knockdown on the growth of breast tumors was significant in xenograft model mice." (PMID 30135378, 2018). "In the validation dataset of TCGA, our results indicated that MCM10 was significantly upregulated in breast tumor tissues, and even higher in the triple negative breast cancer." (PMID 30254986, 2018).
colon cancer (2 papers, 2019 to 2024). "Analysis of dataset GSE29623, an mRNA and microRNA profile in colon cancer, supported that miR-622 positively correlated with signature genes in cell cycle pathway, such as CDC6 (r = 0.421), CDK2 (r = 0.336), CCNE1 (r = 0.423), CCNA2 (r = 0.412), CCNA5 (r = 0.350), and MCM10 (r = 0.423)." (PMID 38166756, 2024). "We selected non-transformed hTERT RPE-1 and colon cancer HCT116 cells, which—unlike hTERT RPE-1—overexpress Mcm10." (PMID 31409229, 2019).
viral diseases (2 papers, 2023). "Isolated deficiencies of ILCs and NK cells in patients with IEIs, such as GINS1, MCM4, or MCM10 deficiency, can lead to various degrees of susceptibility to viral diseases, mostly caused by CMV." (PMID 36736301, 2023). "In some defects, such as deficiencies of MCM4, GINS1, and MCM10, where there is a significant susceptibility to recurrent and severe viral infections, the pathogenesis may be explained by severely defective NK cells." (PMID 36986362, 2023).
congenital cardiomyopathy (1 paper, 2025). "Additionally, LILRA6 has been implicated in rheumatoid arthritis and multiple sclerosis, while MCM10 has been identified in the context of immunodeficiency disease, with or without congenital cardiomyopathy." (PMID 40386946, 2025).
dissection (1 paper, 2021). The separation and isolation of tissues for surgical purposes, or for the analysis or study of their structures. "In summary, our studies showed that MCM2, MCM4, and MCM10 play an important role in aortic dissection and the expression of MCMs was inhibited by atorvastatin treatment." (PMID 33803192, 2021).
endometrial cancer (1 paper, 2023). Primary or metastatic malignant neoplasm involving the endometrium (mucous membrane that lines the endometrial cavity). "The ROC curve showed a well ability of MCM10 protein to distinguish endometrial cancer from normal endometrium (AUC = 0.840, CI: 0.765–0.915)." (PMID 37246638, 2023).
fibrosarcoma (1 paper, 2021). A malignant mesenchymal fibroblastic neoplasm affecting the soft tissue and bone. "The MCM10 fold change of patients with round cell liposarcoma, Malignant fibrous histiocytoma, synovial Sarcoma and fibrosarcoma was 7.893, 7.758, 5.892, and 9.258, respectively." (PMID 34239894, 2021).
lung adenocarcinoma (1 paper, 2021). A carcinoma that arises from the lung and is characterized by the presence of malignant glandular epithelial cells. "However, the mutations that do occur in MCM10 during lung adenocarcinoma arise from a missense mutation." (PMID 33604163, 2021). "Thus far, we have determined that MCM10 is a potential diagnostic marker for lung adenocarcinoma and demonstrated upregulation is necessary for excessive tumor growth." (PMID 33604163, 2021). "The results thus far support the theory that MCM10 expression is a novel marker for lung adenocarcinoma." (PMID 33604163, 2021). "This resulted in four genes of interest, of which MCM10 was both the most often mutated in the TGCA PanCancer atlas and the most poorly covered in the context of lung adenocarcinoma." (PMID 33604163, 2021). "We present evidence that Minichromosome Maintenance 10 (MCM10) is a prominent marker for late stage lung adenocarcinoma." (PMID 33604163, 2021). "Results from qPCR align with our bioinformatic results, suggesting lung adenocarcinoma samples have a much higher level of MCM10 than did normal tissue." (PMID 33604163, 2021). "Our analysis of MCM10 in lung adenocarcinoma involved the integration of several bioinformatics approaches." (PMID 33604163, 2021). "Previous work has established MCM10 is regulated by MYCN, an oncogene known to be mutated in several subtypes of lung adenocarcinoma (Rickman, Schulte & Eilers, 2018)." (PMID 33604163, 2021). "Nearly all expressed transcripts are upregulated in lung adenocarcinoma samples, with the most prominently expressed transcript (MCM10-202) demonstrating a 2.5-fold increase in expression." (PMID 33604163, 2021). "Interestingly, while many of the genes are highly connected, four of the HUB genes upregulated during lung adenocarcinoma (MCM10, MCM4, GINS2 and CD45) are predicted to interact nearly independently through direct binding mechanisms." (PMID 33604163, 2021). "We identify MCM10 as a crucial HUB gene over expressed in lung adenocarcinoma." (PMID 33604163, 2021). "Finally, evaluation of 72 clinical biopsy samples suggests that overexpression of MCM10 in the lung adenocarcinoma highly correlates with larger tumor size." (PMID 33604163, 2021). "The results thus far have led to the hypothesis that MCM10 is a novel marker for lung adenocarcinoma." (PMID 33604163, 2021). "Together, this work suggests that MCM10 may be a clinically relevant gene with both predictive and therapeutic value in lung adenocarcinoma." (PMID 33604163, 2021). "Several published sources suggest that MCM10 may be mutated in other cancers, however our system-based approach suggested that this may not be the case in lung adenocarcinoma." (PMID 33604163, 2021). "Through this, we have demonstrated that MCM10 may be a viable marker for lung adenocarcinoma." (PMID 33604163, 2021). "Therefore, we hypothesize aberrant MYCN function may directly result in amplification of MCM10, which then potentiates lung adenocarcinoma pathogenesis." (PMID 33604163, 2021). "While these results suggest that MCM10 expression is important in lung adenocarcinoma pathogenesis, they do not fully implicate MCM10 in rampant tumor growth." (PMID 33604163, 2021).
osteosarcoma (1 paper, 2022). A usually aggressive malignant bone-forming mesenchymal neoplasm, predominantly affecting adolescents and young adults. "IGFBP5 has been identified as a hub gene in osteosarcoma along with origin recognition complex subunit 6 (ORC6), minichromosome maintenance 10 replication initiation factor (MCM10), MET proto-oncogene, receptor tyrosine kinase (MET) and centromere protein F (CENPF)." (PMID 36465383, 2022).
rectal adenocarcinoma (1 paper, 2020). "MCM10 was also 3.484-fold in colon and 3.309-fold in rectal adenocarcinoma samples lower than relevant normal tissues." (PMID 32597491, 2020).
sarcoma (1 paper, 2021). A usually aggressive malignant neoplasm of the soft tissue or bone. "To explore the prognosis value of MCM10 in sarcoma, we analyzed the data in GEPIA and found that highly expressed MCM10 was associated with poor OS of sarcoma patients, indicating that MCM10 was a potential biomarker of prognosis for sarcoma patients." (PMID 34239894, 2021). "The results showed that MCM1–7 and MCM10 were all upregulated in sarcoma in ONCOMINE database." (PMID 34239894, 2021). "Therefore, MCM2, MCM3, MCM4, and MCM10 were four potential biomarkers for the prognosis of sarcoma and a higher expression indicates worse outcomes." (PMID 34239894, 2021). "The results showed that MCM10 was upregulated in sarcoma compared to normal samples." (PMID 34239894, 2021). "Furthermore, we analyzed the prognostic value of MCMs for sarcoma in GEPIA and found that MCM2, MCM3, MCM4, and MCM10 are prognostic biomarkers for human sarcoma." (PMID 34239894, 2021). "In CCLE, we also found that MCM10 was highly expressed in sarcoma cell lines." (PMID 34239894, 2021). "The results showed that high levels of MCM3 and MCM10 mRNA significantly decreased the over survival (OS) (p < 0.05) and disease-free survival (DFS) (p < 0.05) of sarcoma patients." (PMID 34239894, 2021).